CLCN5 (Cl-/H+ antiporter 5)
Description:
Proton-coupled chloride transporter. Functions as antiport system and exchanges chloride ions against protons. Important for normal acidification of the endosome lumen. May play an important role in renal tubular function. The CLC channel family contains both chloride channels and proton-coupled anion transporters that exchange chloride or another anion for protons. The absence of conserved gating glutamate residues is typical for family members that function as channels (Probable).
Synonyms: ClC-5; CLCK2; DENTS; XLRH; hClC-K2; hCIC-K2; CLC5; XRN; DENT1; NPHL1; NPHL2
Tractability: Small molecule: a structure with a bound ligand is known; it has a high-quality binding pocket; it belongs to a druggable protein family. Antibody: UniProt places it where antibodies can reach, with high confidence; its Gene Ontology location is reachable by antibodies, with high confidence; UniProt predicts a signal peptide or a membrane-spanning region; the Human Protein Atlas places it where antibodies can reach. PROTAC: UniProt records ubiquitination sites on it; ubiquitination databases record sites on it; its protein half-life has been measured.
Gene: Protein-coding gene on chromosome X (49,922,596 to 50,099,235, forward strand). Ensembl gene ENSG00000171365.
Subcellular location: Golgi apparatus membrane; Endosome membrane; Cell membrane
Subcellular location (Human Protein Atlas): Golgi apparatus; Plasma membrane; Cytosol
Pathways (Reactome):
Transport of small molecules: Stimuli-sensing channels
Gene Ontology:
Molecular function: identical protein binding; protein binding; voltage-gated chloride channel activity; antiporter activity; chloride channel activity; chloride transmembrane transporter activity
Biological process: chloride transport; renal system process; monoatomic ion transmembrane transport; chloride transmembrane transport; transmembrane transport
Cellular component: apical part of cell; Golgi apparatus; lysosomal membrane; membrane; plasma membrane; endoplasmic reticulum membrane; endosome membrane; synaptic vesicle; endosome; Golgi membrane
Gene-disease validity (ClinGen):
ClinGen rates the evidence that CLCN5 causes each of these diseases.
Dent disease type 1 (X-linked): Definitive. Dent disease type 1 is a type of Dent disease with predominantly renal manifestations.
Homologues: Orthologues: chimpanzee CLCN5 (100% identical), macaque CLCN5 (99% identical), rabbit CLCN5 (98% identical), rat Clcn5 (98% identical), dog CLCN5 (97% identical), mouse Clcn5 (97% identical), pig CLCN5 (97% identical), guinea pig CLCN5 (93% identical), tropical clawed frog clcn5 (82% identical), zebrafish clcn5a (79% identical), zebrafish clcn5b (75% identical), Drosophila melanogaster ClC-c (59% identical), and 1 more. Paralogues in human: CLCN3 (73% identical), CLCN4 (72% identical), CLCN7 (29% identical), CLCN6 (27% identical), CLCN2 (25% identical), CLCN1 (24% identical), CLCNKA (20% identical), CLCNKB (20% identical).
Diseases named in the same sentence as CLCN5 in open-access papers:
CLCN5 is named in the same sentence as 110 diseases in open-access papers, as found by Europe PMC text mining. Sharing a sentence is not in itself a finding about the gene and the disease. The quoted sentences say what the papers report.
Dent disease (114 papers, 2007 to 2026). Dent disease is a rare genetic renal tubular disease characterized by manifestations of proximal tubule dysfunction. "Dent's disease type 1, accounting for 60% of cases, caused by mutations in the CLCN5 gene encoding the chloride ion channel protein ClC-5, exhibits significant clinical heterogeneity and variability in disease progression." (PMID 41860181, 2026). "It is widely recognized that Dent's disease is associated with a mutation in the CLCN5 gene, leading to proximal tubular dysfunction." (PMID 41311422, 2025). "To date, Dent disease has been reported to be caused by more than 350 CLCN5 variants and 370 OCRL variants." (PMID 40420588, 2025). "CLCN5 is the gene responsible for Dent disease-1 and encodes the voltage-gated chloride channel ClC-5." (PMID 40163114, 2025). "We present the case of a young woman who presented with a full phenotype of Dent disease type 1 due to a de novo mutation in the CLCN5 gene and a skewed X-chromosome inactivation." (PMID 38873575, 2024). "Two types of Dent disease have been identified: type 1 caused by mutations in CLCN5 and type 2 caused by specific mutations in OCRL (other OCRL mutations cause Lowe syndrome) that manifests with a Dent-like phenotype." (PMID 38873575, 2024). "First discovered in 1964, Dent disease consists of two subcategories differentiated by the causative gene, either CLCN5 or OCRL." (PMID 39610999, 2024). "Dent disease type 1 is caused by changes in the chloride voltage-gated channel 5 (CLCN5) gene on chromosome X, resulting in the lack or dysfunction of chloride channel ClC-5." (PMID 39322766, 2024). "Dent disease type 1 is characterized by inactivating mutations of the CLCN5 gene encoding the 2Cl−/H+ exchanger (ClC-5) and is observed in about 65% of patients with Dent disease." (PMID 39336766, 2024). "Approximately 60% of cases are caused by mutations in the CLCN5 gene (Dent disease-1, DD-1), which encodes for the ClC-5 chlorine/proton exchanger, located mostly in early endosomes of the proximal tubule." (PMID 39125679, 2024). "Over 500 families carrying Dent disease-causing mutations were described; among them almost 200 different mutations of CLCN5 lead to Dent disease type 1." (PMID 39336766, 2024). "In fact, mutations in CLCN5 cause Dent’s disease type 1 (DD1), a rare X-linked renal proximal tubulopathy characterized by hypercalciuria and low molecular weight proteinuria." (PMID 38670633, 2024). "As shown in public databases, CLCN5 pathogenic variants also cause hypophosphatemic rickets (OMIM:#300554), renal stone type I (OMIM:#310468) and low-molecular-weight proteinuria with hypercalciuric renal calcinosis (OMIM: #308990)." (PMID 38267993, 2024). "Dent disease type 1 is characterized by pathogenic CLCN5 gene variants and impaired receptor-mediated endocytosis in proximal tubules." (PMID 38256038, 2024). "Mutations in CLCN5, the genetic cause of Dent’s disease type 1 (DD1), lead to PTC epithelial cell dedifferentiation and dysfunction." (PMID 38670633, 2024). "We present the case of a 19-year-old girl affected by Dent disease type 1 (MIM 300009) due to a de novo mutation in the CLCN5 gene with skewed X-inactivation (SXI)." (PMID 38873575, 2024). "Dent disease is a rare nephropathy mainly caused by mutations in the CLCN5 gene encoding the ClC-5 chloride channel that belongs to the voltage-gated chloride channel family (Dent disease type 1; MIM#300009)." (PMID 36674829, 2023). "A variant in CLCN5 was found in one patient (Dent disease), and in NR3C2 in another patient (Geller syndrome)." (PMID 37537162, 2023). "We report the identification of an insertion-deletion CLCN5 variant in three members of the same family, as well as one unrelated paediatric patient with Dent’s disease." (PMID 37641036, 2023). "Dent-1 disease is caused by variants in CLCN5, accounts for 60% of patients with Dent disease and rarely has extra-kidney manifestations." (PMID 35585366, 2023).
Dent disease (continued). "The majority of people with Dent’s disease have pathogenic variants in the CLCN5 (Dent disease 1, roughly 60% of patients) or OCRL1 genes (Dent disease 2, roughly 16% of patients)." (PMID 37641036, 2023). "The majority of cases of Dent’s disease are caused by pathogenic variants in the CLCN5 gene, which encodes a voltage-gated chloride ion channel (ClC-5), resulting in proximal tubular dysfunction." (PMID 37641036, 2023). "Dent’s disease, caused by variants in the CLCN5 (Dent disease 1) or OCRL1 (Dent disease 2) genes, leads to proximal tubular dysfunction in basically all affected patients." (PMID 37597335, 2023). "Dent disease type 1 is an X-linked tubulopathy mainly caused by inactivating mutations in the chloride voltage-gated channel 5 (CLCN5) gene." (PMID 35530822, 2022). "1448delG) at exon 11 of the CLCN5 gene which leads to Dent disease 1, expanding the spectrum of CLCN5 mutations." (PMID 36452359, 2022). "Type 1 Dent disease is caused by changes in chloride voltage-gated channel 5 (CLCN5) gene on chromosome X, which causes the lack or dysfunction of chloride channel ClC-5." (PMID 36284768, 2022). "Dent disease also called X-linked recessive hypophosphatemic rickets is due to mutations in CLCN5 resulting in loss of function of CLCN5 in the proximal tubule which is associated with renal phosphate wasting." (PMID 35352187, 2022). "Mutations in CLCN5, which was encodes a voltage-gated chloride ion channel in the renal tubule, are the major cause of Dent disease." (PMID 35755072, 2022). "In the kidney, CLCN5 encodes a chloride channel Cl-/H+ exchanger ClC-5, which played an important role in preventing protein loss, and this effect was weakened in patients with Dent disease who carried the defective CLC-5." (PMID 36408280, 2022). "Hypercalciuria and LMWP were noted in all four patients with Dent disease, two were Dent-1 caused by CLCN5 mutation, and two were Dent-2 caused by the OCRL1 mutation." (PMID 35612621, 2022). "Dent disease is a rare X-linked tubulopathy caused by mutations either in CLCN5 (Dent disease type 1 (DD1) MIM #300009) or OCRL (Dent disease type 2 (DD2) MIM #300555) genes." (PMID 34680992, 2021). "More than 200 CLCN5 mutations are reported in Dent disease patients, and ~25% have been functionally analysed and classified into three classes according to their impact at the cellular and molecular levels." (PMID 33200471, 2021). "Dent disease type 1 is caused by mutations in the CLCN5 gene that encodes CLC5, a 2Cl−/H+ exchanger." (PMID 33200471, 2021). "The term Dent disease type 2 (MIM #300555) was introduced to distinguish cases with mutations in the OCRL gene from those with CLCN5 mutations (Dent disease type 1)." (PMID 32860533, 2021). "This rare disorder was characterized by hypercalciuria, low molecular weight (LMW) proteinuria and proximal tubular dysfunction, caused by pathogenic variants in CLCN5 (Dent disease 1) or OCRL (Dent disease 2) genes." (PMID 33430795, 2021). "Two types are recognized: Dent disease type 1 is caused by CLCN5 mutations (50%‐60% incidence) and type 2 is caused by OCRL mutations (15% incidence)." (PMID 33200471, 2021). "They described 32 unrelated males with a Dent disease phenotype, 19 (about 60%) of them with a mutated CLCN5 gene (DD1), 5 (about 15%) with a mutated OCRL gene (DD2), and 8 (25%) with no mutations in either gene (DD3)." (PMID 32860533, 2021). "The gene most often involved is CLCN5 (responsible for about 65% of cases), mutations of which are responsible for Dent disease type 1 (DD1)." (PMID 32860533, 2021). "Case 1 revealed a pathogenic variant in exon 11 of CLCN5 gene [NM_001127899; c.1444delG] and a nonsense mutation at nucleotide 1509 [p.L503*], and he was diagnosed as Dent disease." (PMID 33430795, 2021). "Two knock-out (KO) mouse models for Clcn5 were generated in 2000 to shed light on the molecular mechanisms underlying Dent disease." (PMID 32860533, 2021).
Dent disease (continued). "About 50%-60% of patients harbor inactivating pathogenic variants of the CLCN5 gene (Dent disease 1), about 15% have the OCRL pathogenic variants (Dent disease 2), and other yet unidentified genes are likely involved in Dent disease." (PMID 33430795, 2021). "The evidence to support most therapies in Dent disease is poor, which is reflected by highly variable treatment patterns in patients with CLCN5 and OCRL mutations." (PMID 32860533, 2021). "This is hardly surprising, given the phenotypic heterogeneity of Dent disease, and the previously discussed sometimes incongruent results of in vitro experiments on CLCN5 mutations." (PMID 32860533, 2021). "Approximately 60% of Dent disease cases are caused by mutations in the CLCN5 gene, which are referred to as Dent disease 1 (OMIM#300,009)." (PMID 32201916, 2020). "There are two forms of Dent disease, with the most common caused by mutations in the renal chloride transporter CLCN5 (Dent-1 disease) and the less common type caused by mutations in OCRL (Dent-2 disease)." (PMID 31811534, 2020). "Dent disease (DD), an X-linked renal tubulopathy, is mainly caused by loss-of-function mutations in CLCN5 (DD1) and OCRL genes." (PMID 31947599, 2020). "Seven patients in our cohort had specific diagnosis from additional clinical and laboratory findings including cystinosis in three, tyrosinemia in two, Dent diseases with CLCN5 mutation in one and McCune Albright syndrome in one patient." (PMID 31514490, 2020). "Female Dent disease 1 patients with low-molecular-weight proteinuria (LMWP) due to CLCN5 gene mutation were rarely reported, and these cases that the people were also with Turner syndrome (TS) were even hardly documented before." (PMID 32393202, 2020). "Taken together, Dent disease should be taken into consideration with the missense mutation in CLCN5 with incomplete phenotype." (PMID 32725812, 2020). "The proximal tubule represents the site of greatest calcium reabsorption within the renal tubule, and it is mutations in the ClC-5 chloride transporter in this region, encoded by CLCN5, that give rise to Dent disease type 1." (PMID 31935940, 2020). "In this paper, we describe a patient developed C3 nephropathy during flare of psoriasis who was further diagnosed with CLCN5 (*300008) mutation for diagnosis of Dent disease (*300009)." (PMID 32725812, 2020). "A hemizygouse mutation of CLCN5 (*300008, c.1904A>G,p.Asn635Ser) was identified for diagnosis of Dent disease (*300009)." (PMID 32725812, 2020). "Dent disease type 1 (DD1) is caused by mutations in the CLCN5 gene encoding ClC‐5, a Cl−/H+ antiporter localized to early endosomes of the proximal tubule (PT)." (PMID 31472005, 2019). "Dent disease, characterized by a specific renal phenotype, is caused by truncating mutations of CLCN5 in the majority of affected cases." (PMID 30630535, 2019). "Dent disease-1 is a rare X-linked recessive renal tubular disorder caused by pathogenic variants in the chloride voltage-gated channel 5 (CLCN5) gene." (PMID 29084614, 2017). "We demonstrated that NP is a common finding in Dent disease both in patients with CLCN5 and OCRL mutations." (PMID 27757584, 2017). "This is the first report of a CLCN5 pathogenic variant in a Dent disease-1 family of Sri Lankan origin, and it highlights the value of genetic evaluation in children with refractory proteinuria." (PMID 29084614, 2017). "Dent disease is a rare X-linked recessive proximal tubulopathy caused by mutations in CLCN5 (Dent-1) or OCRL (Dent-2)." (PMID 27757584, 2017). "Approximately 50-60% of cases with Dent disease have CLCN5 mutations, 15-20% have OCRL mutations and the remaining cases have no detectable mutation." (PMID 29280738, 2017). "Mutations in CLCN5 gene cause a subtype of Dent’s disease type 1 (prevalence: 250 reported families), a renal tubular disorders characterized by low molecular weight proteinuria, hypercalciuria, nephrolithiasis, nephrocalcinosis, and progressive renal failure." (PMID 27242528, 2016).
Dent disease (continued). "This progression is in line with histological findings in patients with Dent-1 disease due to variants in CLCN5." (PMID 27011217, 2016). "The Xp11.22 deletions with loss of CLCN5 gene allowed us to confirm the diagnostic of Dent disease for our patient." (PMID 25670966, 2015). "DD is caused by mutations in the CLCN5 gene, which encodes the electrogenic chloride/proton exchanger ClC-5 (this condition is now called Dent disease 1, OMIM 300009) (DD1)." (PMID 26389017, 2015). "Mutations in CLCN5 have been found in Dent disease, an X-linked inherited renal condition characterized by proteinuria, hypercalciuria and hyperphosphaturia, kidney stones, and in some cases, kidney failure." (PMID 25670966, 2015). "The clear association between genetic alternations in CLCN5 and Dent's disease has motivated numerous investigations of the molecular mechanisms underlying the renal pathophysiology observed in the affected patients." (PMID 26042048, 2015). "Recently, an atypical Dent’s disease phenotype was found to be due to co-inheritance of mutations in both CLCN5 and OCRL." (PMID 25019425, 2014). "Dent disease 1 represents a hereditary disorder of renal tubular epithelial function associated with mutations in the CLCN5 gene that encoded the ClC-5 Cl-/H+ antiporter." (PMID 25001568, 2014). "In this case, the search for genes underlying Dent's disease, an inherited kidney disorder, identified the CLCN5 gene and sequence variations in Dent's patients." (PMID 23226131, 2012). "In order to confirm a diagnosis of Dent's disease, molecular genetic analysis was performed one year later and showed a mutation in the CLCN5 gene, leading to S244L amino acid substitution." (PMID 21859490, 2011). "Dent’s disease 1 is caused by mutations in the renal chloride channel CLCN5 that encodes a kidney-specific voltage gated chloride channel." (PMID 21448331, 2011). "Dent's disease is caused by mutations in the CLCN5 gene, which is located on the short arm of the × chromosome (Xp11.22)." (PMID 21859490, 2011). "Dent's disease is a renal tubular disorder caused by mutations in either the CLCN5 (Dent disease 1) or OCRL1 (Dent disease 2) genes that are located on chromosome Xp11.22 and Xq25, respectively." (PMID 20946626, 2010). "The disease is caused by mutations in either the CLCN5 (Dent disease 1) or OCRL1 (Dent disease 2) genes that are located on chromosome Xp11.22 and Xq25, respectively." (PMID 20946626, 2010). "If the mother or siblings of a patient with Dent's disease are eager to know their genetic status and risk for developing the disease, then mutational analysis of CLCN5 and/or OCRL1, using leukocyte DNA can be undertaken." (PMID 20946626, 2010). "Dent disease is a rare X-linked recessively inherited renal tubulopathy, caused by variants in the CLCN5 (Dent disease type 1, DD1) and OCRL (Dent disease type 2, DD2) genes, and characterized by low molecular weight proteinuria, hypercalciuria, microscopic hematuria, or nephrocalcinosis." (PMID 40420588, 2025). "In addition, X-linked recessive hypophosphatemic rickets is associated with pathogenic variants in chloride voltage-gated channel 5 (CLCN5)." (PMID 41445557, 2025). "X-linked recessive hypophosphatemic rickets is due to CLCN5 variants." (PMID 40533633, 2025). "Dent disease type 1 is caused by sequence variants in CLCN5 that alter ClC-5 protein functions." (PMID 38233994, 2024). "Data suggests that female carriers of inactivating variants in CLCN5 may have mild symptoms of Dent disease such as low-molecular-weight proteinuria, and hypercalciuria with few reported cases of NL and kidney insufficiency." (PMID 38606357, 2024). "Dent disease with pathogenic variants in both the CLCN5 and OCRL1 genes has also been reported, but the causative genes in 25% of Dent disease patients are still unknown and are collectively referred to as Dent disease type III." (PMID 38267993, 2024).